STAT4 (signal transducer and activator of transcription 4)
Diseases named in the same sentence as STAT4 in open-access papers (continued):
Sharing a sentence is not in itself a finding about the gene and the disease.
ovarian carcinoma (19 papers, 2010 to 2024). A malignant neoplasm originating from the surface ovarian epithelium. "Concerning the role of STAT4 in cancer, there are reports in ovarian cancer showing that STAT4 expression is associated with a poor prognosis and metastasis." (PMID 33076315, 2020). "Interestingly, a contrasting study showed a direct relationship between STAT4 expression and tumor development in ovarian cancer, where its overexpression was associated with epithelial-to-mesenchymal transition of cancer cells, resulting in metastasis." (PMID 32010142, 2019). "Similarly, STAT4 expression has been linked to improved survival in breast and late-stage ovarian cancer, while decreased levels of phosphorylated STAT4 in peripheral blood mononuclear cells is associated with metastasis in melanoma patients." (PMID 32010142, 2019). "In another study, STAT4 protein overexpression induced by hypoxia accelerated the progression of EMT in ovarian cancer cells, which was negatively regulated by miR‐200a via targeting STAT4." (PMID 38107057, 2023). "Ovarian cancer patients with a high level of STAT4 and 6 gene expression or a low level of STAT1 gene expression had high OS." (PMID 36524006, 2022). "Signal transducer and activator of transcription 4 has been identified as an oncogene in gastric cancer, ovarian cancer, and CRC." (PMID 34276757, 2021). "Overexpression of STAT4 mRNA was significantly related to a favorable OS for all the ovarian cancer patients, HR =0.81 (0.70−0.92), P=0.0015, serous cancer patients, HR =0.78 (0.65−0.93), P=0.0054." (PMID 28536310, 2017). "In this report, our results show that higher mRNA levels of STAT4 are significantly correlated to a better OS for all the ovarian cancer patients, especially serous cancer patients." (PMID 28536310, 2017). "In contrast, there are more defined roles of MAKP10 and STAT4 in ovarian cancer." (PMID 37095524, 2023). "The programmed cell death mediated by MAPK10 and STAT4 in ovarian cancer deserves further study." (PMID 37095524, 2023). "In epithelial ovarian cancer, the elevated expression of STAT4 in epithelial cells induced MSCs derived from adipose and bone marrow to obtain CAF-like features, which in turn promoted EMT and peritoneal metastasis of ovarian cancer by secreting CXCL12, IL-6 and VEGF-A." (PMID 36185262, 2022). "The exact role of STAT4 in tumorigenesis remains unclear because high levels of STAT4 expression have been shown to promote invasion and metastasis in gastric cancer and ovarian cancer, and potentially predict a favorable outcome in these cancers." (PMID 36061181, 2022). "Although high STAT4 expression is a favorable prognostic factor in hepatocellular, breast, and ovarian cancers, the exact role of STAT4 in cancer remains unclear." (PMID 35873566, 2022). "Likewise, STAT4 could induce activation of tumor-associated fibroblasts (CAF) through tumor-derived Wnt7a, which promoted peritoneal metastasis of ovarian cancer through the EMT process." (PMID 36524006, 2022). "This study demonstrated that CD24 induced the expression of miR-130a and 301a via Src or FAK-mediated STAT4 and YY1 phosphorylation in ovarian cancer cells, which led to cellular quiescence-like state and chemoresistance." (PMID 38360723, 2024). "With regard to clinical stages, while STAT5a, STAT5b, and STAT6 were related to a positive OS both in stages I/II and III/IV ovarian cancer patients, STAT1 and STAT4 were correlated to a favorable OS in stages III and IV ovarian cancer patients." (PMID 28536310, 2017). "It is suggested that STAT1, STAT4, and STAT6 may be potential targets for the proper treatment of ovarian cancer." (PMID 36524006, 2022). "Based on our findings, STAT1, STAT4, and STAT6 may be viable therapeutic targets for ovarian cancer." (PMID 36524006, 2022).
ovarian carcinoma (continued). "In summary, our results show that high mRNA expression of all the individual STATs except STAT2 and STAT3 are correlated to a better OS for all the ovarian cancer patients, especially the high level of STAT1 and STAT4 are significantly related to a favorable OS for serous ovarian cancer patients." (PMID 28536310, 2017). "Our results show that high mRNA expression of STAT1, STAT4, STAT5a, STAT5b, and STAT6, are correlated to a better OS of ovarian cancer patients, especially the high level of STAT1 and STAT4 are significantly related to a favorable OS for serous ovarian cancer patients." (PMID 28536310, 2017). "High expression of STAT1, STAT3, STAT4, and STAT6 mRNA were correlated to a better OS in grade III ovarian cancer patients, but not in grade I or II ovarian cancer patients." (PMID 28536310, 2017). "Here we found that phosphorylation of STAT1, as well as STAT4 and STAT6 (not shown) were simultaneously activated by PAF treatment in BRCA1-mutant ovarian cancer cells (UWB1)." (PMID 20576130, 2010). "Furthermore, we found that STAT4 mRNA levels predicted an improved OS in grade III and stage III/IV but not grade I/II and stage I/II ovarian cancer patients, suggesting that this gene is a favorable prognosis indicator especially for late stage and poor differentiation in ovarian cancer patients." (PMID 28536310, 2017).
diabetes (18 papers, 2013 to 2025). "It was further revealed that both Asians and Caucasians with the STAT4 rs7574865 polymorphism have an increased diabetes risk." (PMID 30044774, 2018). "Also, a meta-analysis study performed on Caucasians and Asian subjects showed that it was associated with diabetes risk (P < 0.5), and there was a study that confirmed the STAT4 was overexpressed from T1D Polish patients." (PMID 34342790, 2021). "The extensive literature implicating inflammation in diabetes and many progressive neurodegenerative diseases, including AD, makes Stat4 a therapeutic target with immense potential for slowing, or even preventing, neurodegenerative disease progression." (PMID 37783748, 2023). "STAT4 is an important mediator of inflammation in immune cells and fat cells in diabetes and obesity." (PMID 34176465, 2021). "Activated STAT4 has an inflammatory effect, and STAT4 is an important mediator of inflammation in diabetes." (PMID 34176465, 2021). "Variants in the signal transducer and activator of transcription 4 (STAT4) gene have an important role in the incident of multiple autoimmune diseases including type 1 diabetes mellitus (T1D)." (PMID 34342790, 2021). "Further, STAT4 mediates inflammatory responses in immune cells and adipocytes in diabetes and obesity." (PMID 30044774, 2018). "In experimental diabetes, a genetic disruption of STAT4 activation prevented the spontaneous development of diabetes in NOD mice." (PMID 26555476, 2015). "Numerous inflammatory cytokines in the brain are released in diabetes and neurodegenerative diseases, and it remains to be determined which inflammatory signals are essential for the phosphorylation and activation of Stat4 resulting in down-regulation of synaptic plasticity." (PMID 37783748, 2023). "It has been reported that CBL might alleviate endothelial dysfunction in patients with diabetes mellitus by inactivating the JAK2/STAT4 signalling pathway." (PMID 36726727, 2023). "Disruption of STAT4 activation completely prevents the development of spontaneous diabetes in mice." (PMID 34798872, 2021). "Agents that disrupt IL-12 signaling or STAT4 signaling may be effective therapeutic tools to prevent or treat diabetes." (PMID 26555476, 2015). "Modulation of IL-12/STAT4 signaling may be a valuable therapeutic strategy to preserve islet/β-cell viability in established diabetes." (PMID 26555476, 2015). "In terms of diabetes, NOD mice deficient in STAT4 do not develop spontaneous diabetes unlike wild-type NOD mice." (PMID 26555476, 2015). "Additionally, lisofylline, which inhibits STAT4 activation, also provides protection against diabetes development." (PMID 23437231, 2013). "We hypothesize that Stat4 may be a final common pathway mediator of inflammatory damage that is important in normal aging, diabetes and AD, and that therapies that prevent Stat4 activation have potential as novel treatments for such slow, progressive neurodegenerative diseases." (PMID 37783748, 2023). "Stat4 appeared to prevent aging-associated declines in magnitude of long-term potentiation (LTP) of synaptic transmission, suggesting that it plays an important role in inflammation that contributes to metabolic disease and aging and diabetes-associated cognitive decline." (PMID 37783748, 2023). "Therefore, STAT4 is an important mediator of inflammation in immune cells and adipocytes in diabetes and obesity and sustained activation of STAT4 in skin wounds may contribute to perpetuation of inflammatory responses and impaired healing." (PMID 28107529, 2017). "We delved deeper into the specifics of MAM protein-protein interactions and discovered key connections between many of the altered MAM proteins in diabetes with several major protein regulators of inflammation, diabetes, and/or DR, specifically IL-1β, NFκBIA, FOXO1, SYVN1, STAT4, MAF, and LGALS3." (PMID 36139394, 2022).
diabetes (continued). "The absence of STAT4, in both streptozotocin-induced and spontaneous diabetes, protects against the development of diabetes." (PMID 23437231, 2013). "Serum levels of IFNγ and IL12 are reduced in Stat4-/-NOD (non-obese diabetic) mice, and the development of diabetes in NOD mice is prevented with the absence of Stat4." (PMID 32226303, 2020).
psoriasis (18 papers, 2010 to 2025). An autoimmune condition characterized by red, well-delineated plaques with silvery scales that are usually on the extensor surfaces and scalp. "There are several polymorphisms associated with risk of psoriasis, including signal transducer and activator of transcription 4 (STAT4), TaqI polymorphisms in vitamin D receptor (VDR) gene, interleukin-10 (IL-10) polymorphisms and LCE3B genes." (PMID 24324571, 2013). "Other genes associated with psoriasis include signal transducer and activator of transcription 4 (STAT4), apoliprotein E (APOE), vitamin D receptor (VDR), and cytotoxic T lymphocyte-associated protein 4 (CTLA4)." (PMID 24069534, 2013). "In SSc, the newly reported candidate genes and risk loci include CD247, MHC, IRF5, and STAT4 gene regions, psoriasis susceptibility 1 candidate (PSORS1C) 1, TNIP1, and putative one close to ras homolog gene family, member B (RHOB) gene." (PMID 22110541, 2012). "The genes associated with psoriasis that encode players in the JAK-STAT pathway are STAT4 and TYK2." (PMID 37569685, 2023). "In the context of melanoma and psoriasis, a better understanding of how Lck, IL-12p70 and STAT4 regulate signalling pathways in these divergent pathologies appears warranted." (PMID 40868162, 2025). "An association with STAT4 was first identified in RA and SLE, but later also found in SSc, inflammatory bowel diseases, type 1 diabetes, psoriasis, and primary antiphospholipid antibody syndrome." (PMID 22110541, 2012). "Regarding the STAT4 gene, the rs7574865 GG genotype was less frequently observed in the psoriasis cases, suggesting it may act as a protective factor against the disease." (PMID 40343299, 2025). "Genome-wide association studies (GWAS) have established a relationship between the JAK-STAT pathway and IMIDs, For example, JAK2, Tyk2, STAT1, STAT3, STAT4, and IBD; TyK2, TAT1, SLE; TyK2, STAT4, RA; and TyK2, STAT3, and psoriasis are closely linked to the JAK-STAT pathway." (PMID 37351513, 2023). "No significant changes in p-STAT4 for the psoriasis-associated variant rs34536443 was found." (PMID 29728633, 2018). "Activation of STAT4 can lead to specific Th1 differentiation, potentially intensifying responses to interferon (IFN)-γ and triggering psoriasis." (PMID 40343299, 2025). "IKZF1 has been suggested to affect the STAT4 and IFN pathways, both of which involve in the pathogenesis of psoriasis." (PMID 29715312, 2018). "Genes co-expressed with B3GNT2 in macrophages were located next to intergenic sequences with elevated density of motifs recognized by TFs important to psoriasis pathogenesis, such as IRF1, STAT4 and STAT5 (Part B)." (PMID 24885462, 2014). "Our results suggest new hypotheses for interpretation of intergenic hits from psoriasis GWAS studies, and we have identified SNPs predicted to influence binding of AP-1, NF-κB, IRF1, STAT3 and STAT4." (PMID 24885462, 2014). "Moreover, IL-12p70 activates STAT4 which is thought not to be involved in the pathogenesis of psoriasis in contrast to STAT3 which acts as a key player in the psoriasis-inducing interleukin-23/interleukin-17 (IL-23/IL-17) axis." (PMID 40868162, 2025). "In contrast to Lck-mediated psoriasis, STAT4 is not involved." (PMID 40868162, 2025).
viral infection (17 papers, 2011 to 2025). "Moreover, impaired CD8+ T cell expansion in response to viral infections has been reported earlier in STAT4-deficient mouse models, that is also associated with higher STAT1 levels." (PMID 36072585, 2022). "Increase in STAT1, during viral infections, by type 1 IFN or IFNγ, have been associated with decreased STAT4 access to receptors." (PMID 36072585, 2022). "On the other hand, a recent study concluded that T-bet and STAT4 are actually required for GC Tfh development and GC formation during acute viral infection." (PMID 32634740, 2020). "Thus, the balance between STAT1 and STAT4 activation in NK cells would be altered during viral infections." (PMID 36826612, 2023). "Indeed, although type 1 IFN predominantly uses the STAT1 pathway, leading to anti-proliferative effects, viral infection induces predominant STAT4 expression and promotes IFNγ." (PMID 33013883, 2020). "However, STAT1 represses whereas STAT4 activates IFNγ expression in T cells during a viral infection." (PMID 31228946, 2019). "Work by others in CD8+ T cells has shown that reduced levels of STAT1, maintained by STAT4, are required for overcoming the antiproliferative effects of type I IFN during viral infection." (PMID 39560988, 2024). "LOF mutations in STAT1 and TYK2 increase susceptibility to bacterial and viral infections, while LOF in STAT2 increases the incidence of viral infections and LOF in STAT4 increases the incidence of fungal infections." (PMID 35337171, 2022). "STAT4 is activated by phosphorylation mostly in response to IL-12 and IFN-I and promotes IFNγ production during viral infection." (PMID 35182467, 2022). "As summarized in this review, Tfh cell-related transcription factors including Bcl6, IRF4, STAT1/STAT4/STAT5, T-bet, TCF-1, LEF-1, TOX2, Bach2, FOXP1, and KLF2 are all involved in the virus infection." (PMID 32766317, 2020). "During the early phase of viral infections, STAT4 becomes activated initiating a fast IFN-γ response followed by STAT1 activation, which replaces STAT4 at the IFNAR receptor decreasing the ability to produce IFN-γ." (PMID 31781102, 2019). "STAT4 stands as a central factor that links several genes such as type I IFN and ISGs, playing roles in the immune response to viral infections." (PMID 24614210, 2014). "Of these, STAT4 transduces IL12 and IFN-A cytokine signals in T cells and monocytes whereas IL7 is critical for proper T cell response and expansion during viral infection." (PMID 21901105, 2011). "Notably, STAT4 has been implicated in the exacerbation of chronic CVB3 myocarditis, indicating that therapeutic strategies aimed at STAT4 might inadvertently aggravate prevalent viral infections such as CVB3, thereby exacerbating chronic inflammatory cardiac conditions." (PMID 41222876, 2025).
gastric cancer (16 papers, 2019 to 2025). A primary or metastatic malignant neoplasm involving the stomach. "Recent discoveries have highlighted that miR-141-3p represses gastric cancer-induced transition of normal fibroblasts and BMSCs to cancer-associated fibroblasts by targeting STAT4." (PMID 38737443, 2024). "MiR-141-3p not only restricted the migration and invasion of gastric cancer cells, but also inhibited the transformation of normal fibroblasts (NFs) into cancer-associated fibroblasts (CAFs) by targeting the STAT4/WNT/β-catenin pathway." (PMID 37949959, 2023). "Up to now, up-regulated STAT4 mRNA has been found to be significantly correlated with IFN-γ in patients with gastric cancer and it has been linked to improved disease-free survival." (PMID 36968603, 2023). "Moreover, it has been demonstrated that among STAT proteins, STAT4 can determine the prognosis of gastric cancer due to its association with high levels of dendritic cells and CD8+ T cells, whereas STAT3 and STAT6 have minimal prognostic value." (PMID 31569687, 2019). "In another study, it was demonstrated that miR-141 expression was decreased in H. pylori-positive tissues and that this low expression correlated with a higher invasion ability of gastric cancer cells through the STAT4 pathway." (PMID 38883131, 2024). "MiR-141 suppresses the development of gastric cancer cells and inhibits the differentiation of hBMSCs into CAFs by targeting STAT4." (PMID 37993769, 2023). "In patients with gastric cancer, high expression of STAT4 indicates better disease-free survival, and STAT4 expression being a significant factor in tumor recurrence." (PMID 34638338, 2021). "Studies have found that STAT4 is closely related to the prognosis of a variety of cancers, such as breast, liver, and stomach cancers." (PMID 32063749, 2020). "Since the expression of STAT4 in gastric cancer cells is low or undetectable, we evaluated the correlation of STAT5A and PD-L1 in the further investigation." (PMID 32391259, 2020). "A previous study demonstrated that STAT4 is critically involved in gastric cancer metastasis." (PMID 37095524, 2023). "Additionally, among 62 patients suffered gastric cancer, those with low STAT4 expression have poorer prognosis." (PMID 38107057, 2023). "Furthermore, miRNA-141-3p inhibits the viability and metastasis of gastric cancer cells through the upregulation of STAT4." (PMID 31569687, 2019). "Therefore, targeting the STAT4 pathway and increasing miR-141 expression may be beneficial in patients with gastric cancer." (PMID 38883131, 2024). "Several identified hub genes, including CXCL1, CCL20, IL12B, STAT4, and CD80, are involved in chemokine signaling, immune modulation, and inflammation, which can promote H. pylori–mediated gastric cancer." (PMID 40445003, 2025). "STAT4 is considered as CD8+ T related and favorable prognostic marker in gastric cancer." (PMID 38107057, 2023).
inflammatory bowel disease (16 papers, 2010 to 2025). A spectrum of small and large bowel inflammatory diseases of unknown etiology. "We therefore investigated the influence of STAT4 variants on the susceptibility and phenotype of inflammatory bowel diseases (IBD) in a large patient and control cohort." (PMID 20454450, 2010). "Additionally, a significant inverse correlation with T-risk alleles at rs7574865 and the methylation status of the STAT4 promoter was demonstrated in inflammatory bowel disease." (PMID 23990947, 2013). "In patients with inflammatory bowel diseases (IBDs), DNA methylation of STAT4 promoter is lower than in healthy individuals." (PMID 40214477, 2025). "The recently completed GWAs reported a significant connection between PBC and STAT4, which is also the prominent risk gene in AITD, type 1 diabetes, SLE, RA, SS, and inflammatory bowel disease (IBD)." (PMID 28191014, 2017). "In laminar propria lymphocytes of inflammatory bowel disease patients, LIF-activated STAT4 inhibits activation of the STAT3-dependent Il17a/Il17f promoter, while in intestinal epithelial cells, LIF bypasses abnormally low STAT4 levels and induces YAP gene expression by activating STAT3." (PMID 33505963, 2020).